CD4 (CD4 molecule)
Diseases named in the same sentence as CD4 in open-access papers (continued):
Sharing a sentence is not in itself a finding about the gene and the disease.
tumor (continued). "Actually, tumor microenvironment and host immunity are significantly associated with outcome in patients with MCL since AMC and absolute CD4+ T cell counts (ACD4C) have been confirmed to be significant predictors of unfavorable OS 22,23." (PMID 32742445, 2020). "Collective data from all six developed multiplex panels, with phenotypes combinations after analysis of three tonsils and three selected AITL cases, with reference to the GC CD4+PD-1+ cells in tonsils and to CD4+PD-1+ cells in the Tumor niche in AITL cases." (PMID 33633728, 2020). "Neutrophils contribute to tumor control and tumor eradication also by regulating the activation and function of adaptive immune cells like CD4 or CD8 T cells." (PMID 32580431, 2020). "The previous studies found that increased CD4+ and CD8+ T cells were associated with tumor progression and poor prognosis in RCC." (PMID 33101364, 2020). "The results indicated a significant rise in CD4+CD25+/CD4+ ratio, along with an average increase in tumor mass of the subjects that underwent protein treatment." (PMID 32306719, 2020). "The role of NKT cells, however, remains less understood, with Th2 cytokine-producing tumor-promoting and anti-tumor CD4+ NKT cells that accumulate in the TME." (PMID 33718121, 2020). "These effector T-cells, along with CD4 + T helper cells, are trafficked to the tumour site via chemokine gradients." (PMID 33148287, 2020). "The recruitment of various types of immune cells, such as Tregs, CD4+ T cells, CD8+ T cells, tumor-associated macrophages, and natural killer cells, plays a distinct role in promoting either tumor cell survival or clearance." (PMID 32514188, 2020). "At the same time, the tumor promotes the recruitment of CD4+ Tregs that neutralize anti-tumor immune cells." (PMID 32630174, 2020). "CD4-Th1-like cells expressing high levels of Tbx21, Gzmb, and Ifng had been shown to have anti-tumor capability through activating monocytes and responding to interferon-γ46." (PMID 32709844, 2020). "We observed the densities of CD8+ T cells and CD4+ T cells in the tumor core were significantly less compared to the tumor edge." (PMID 32377339, 2020). "In multivariate analysis, we found that a higher number of CD4+FOXP3+ T cells in the tumor core was an independent predictor of prolonged survival (HR = 0.238, P < 0.001)." (PMID 32377339, 2020). "Quantitative PCR and nanostring analysis of RNA isolated from these tumors revealed increased immune cell markers involved in mediating anti-tumor immunity, most notably CD4, CD8, IFN-γ, TNF-α, granzyme B, CD28, CD11c and CD11b are elevated in K46M mice." (PMID 32896273, 2020). "Tumor cell lysate-based vaccination therapy in combination with immunotherapy targeting CD40 resulted in the induction of IFN-γ secretion from CD4+ T cells and prolonged survival." (PMID 33374542, 2020). "Findings: We identified the heterogeneity underlying tumor immune signature in OSA, and found CD4+ T cells and macrophage markers CD4/IFNGR2/CD68 to be feasible prognostic factors, exerting significantly positive correlation with each other." (PMID 32850346, 2020). "Not only DEVs induce stimulation of naïve CD4+ T cells, but also these EVs are also used by mature DCs as a source of tumor antigens." (PMID 33260499, 2020). "We also reported recently that VVTK-RR-/GFP can increase effector cytotoxic CD4+ T cell activation by increasing the human leukocyte antigen (HLA) class II tumor antigen presentation by tumor cells." (PMID 32995481, 2020). "OvC-PDE retained viable tumour infiltrating lymphocytes (TILs), presenting both CD4+ and CD8+ T cells." (PMID 33173111, 2020). "Of note, also CD4+ T helper cells in our tumor model showed reduced functionality as reflected by reduced production of IFNγ." (PMID 33344239, 2020).
tumor (continued). "In the process of tumorigenesis, Tregs inhibit TCR-mediated activation and proliferation of CD4+/CD8+ T cells to promote tumor immune evasion." (PMID 33344447, 2020). "CD4+ T cells and tumors interact in the tumor microenvironment (TME), and this interaction is a strong determinant of tumor growth or eradication." (PMID 32604872, 2020). "TNS1 expression was significantly correlated with tumor purity, macrophages (r = 0.602, P = 3.15e–41), CD4+ T cells (r = 0.527, P = 3.92e–30), dendritic cells (r = 0.468, P = 3.19e–23), and neutrophils (r = 0.403, P = 4.38e–17)." (PMID 32315285, 2020). "Our findings argue for the therapeutic potential of approaches focused on maximizing the impact on CD4+ Th-ctx activity through manipulation of the Blimp-1/Bcl6 axis in tumor-reactive CD4+ T cells." (PMID 31924474, 2020). "The number of CD4 + cells in primary tumours among rats in the RFA-OK-432 group was also significantly higher than that among rats in the control, RFA-only, and OK-432 groups (all P < 0.05)." (PMID 32541941, 2020). "Tumor immune escape is related to a decline in T cell responses, mainly manifested by immune tolerance to CD4+ T cells and the inhibition of CD8+ T cell activation." (PMID 32571262, 2020). "CD4+CD25+FOXP3+ effector regulatory T cells (Tregs) infiltrate into the tumor stroma as well as tumor-draining lymph nodes and potently suppress anti-tumor immunity." (PMID 33324425, 2020). "Tumor analysis revealed that the response to ICPi often correlates with the pre-existence of an immunologically privileged tumor microenvironment characterized by the presence of CD4/CD8 T cells, immune checkpoints, and pro-inflammatory cytokines." (PMID 32707692, 2020). "The lowest concentration (1 mg kg−1) of JNJ28 slightly, but significantly, reduced tumour size and increased the percentage of CD4+ T cells in TDLN." (PMID 31748740, 2020). "VISTA expression in ICs positively correlated with some tumor-infiltrating lymphocytes (TILs) types, particularly with the CD4+TILs, which was consistent with mRNA level analysis from the TCGA database." (PMID 33505908, 2020). "In support of this assumption, we detected an increased number of CD4+ T cells in the orthotopic tumor, while the number of CD8+ T cells was comparable between both tumor localizations." (PMID 33383676, 2020). "Together, the mouse and human data support a model in which Treg cells control acquisition of cytotoxic activity by tumor-infiltrating CD4+ T cells." (PMID 31924474, 2020). "The mean number of tumor-infiltrating CD4+, CD8+, and CD163+ cells was 142 (range 2-580), 113 (range 1-540), and 170 (range 3-624) per high-power field, respectively." (PMID 33457428, 2020). "IL9 is a cytokine released from the CD4 subset of Th9 cells that is involved in the anti-tumor response." (PMID 32483272, 2020). "To obtain a clearer understanding of the T-cell immune microenvironment in TETs, we analyzed the T-cell profiles of tumor tissues from surgically resected TETs, with a specific focus on CD4 and CD8 single-positive T cells." (PMID 32132638, 2020). "In the context of tumours, a large number of Treg cells were often detected, which inhibited or reduced these effector lymphocytes, such as CD4+ T cells and CD8+ cytotoxicity T lymphocytes (CTL), achieving antitumour immune responses." (PMID 33041668, 2020). "Here, we characterize TILs in a cynomolgus macaque tumour model in which the tumours were infiltrated with CD4+ and CD8+ T cells and were eventually rejected." (PMID 32439888, 2020). "They reported that VEGFR2-blockade alone increased PD-1 expression on CD4+ cells in the tumor but when combined with anti-PD-1 therapy, CD4+ cells’ functions were restored and aided in normalization of vessel formation." (PMID 33117354, 2020). "Such meaningful immune responses, able to control or eradicate tumour growth, have been characterised by the generation of potent tumour antigen specific CD4+, CD8+ T-cells and B-cells in the tumour microenvironment." (PMID 32650622, 2020).
tumor (continued). "In our case, we can also suggest that a part of the Tregs accumulating in the tumor are aimed at inhibiting Th1+ CD4+ T cells." (PMID 32182707, 2020). "The frequency of expression of almost all immune markers, except for CD73 on CD4+ T cells, was higher in the tumor microenvironment than in PBMCs from patients with GBM and PBMCs from healthy donors." (PMID 32721947, 2020). "Several studies have detected neoantigen-specific CD4+ T cells whose induction can control the tumour and, in murine models, the spread of antigen." (PMID 32610601, 2020). "Although CD4 memory help functions seem to directly influence PD-L1/PD-1 inhibitor effects on CD8 anti-tumor responses, the molecular mechanisms by which both populations interplay during PD-L1/PD-1 blockade therapy remain to be fully understood." (PMID 33329566, 2020). "In a transgenic mouse model for pancreatic ductal adenocarcinoma (PDAC), where FAP expressing cells were depleted by injecting diphtheria toxin, CAF depletion led to reduced tumor growth, which was mediated by enhanced CD4+/CD8+ T cell activity." (PMID 32899119, 2020). "T-bet+Foxp3+CD4+ T cells mediated by the immunosuppressive cytokine TGF-β accumulate in the lungs of tumour-bearing mice and are characterized as Th1-like Tregs." (PMID 32680511, 2020). "The ratio of CD4 + T cells to CD8 + T cells was significantly changed in the GL-261 LGALS9−/− tumor-bearing mouse CSF." (PMID 33093453, 2020). "The developing tumor induces an immune reaction driven by IFN-γ producing CD4+T cells that are recruited to the tumor and induce cell death." (PMID 33050416, 2020). "In more detail, pericytes seem to be crucial for recruiting immune cells into the tumor niche and orchestrating an immune–vascular crosstalk involving CD4/CD8 T cells and pericytes." (PMID 33203154, 2020). "In a cohort of 306 CCA samples, the IHC staining demonstrated that high tumor infiltration with CD4+ TILs is a protective factor; indeed, it correlates with a longer patient OS." (PMID 32781527, 2020). "RS cells express factors (including galectin-1, CCL17 and CCL22) that recruit CD4 T cells to the tumor, and promote their differentiation into TH2 and Treg cells." (PMID 32542010, 2020). "As in the case of CXCL9, IRF5 (interferon regulatory factor 5) can bind to the promoter of CXCL13 and directly regulate its expression in mammary epithelial tumor cells leading to the infiltration of CD19+CXCR5+ B-cell and CD4+CXCR5+ T-cell to the tumor." (PMID 33304345, 2020). "With regard to neo-antigen vaccines, a vast majority of immunogenic neo-epitopes is recognized by CD4+ T cells in tumor-bearing C57BL/6 mice." (PMID 33353155, 2020). "SCARF1 within HCC was largely associated with tumor endothelial cells and adhesion studies suggested that it played a role in the specific recruitment of proinflammatory CD4+ T cells (CD4+CD25−) to HCC tumor tissues." (PMID 34354939, 2020). "We saw a higher frequency of CD3-CD19- (putative NK) cells and F4/80+ cells in subcutaneous tumours and a higher frequency of CD3+ CD4+ cells in intracaecal tumours." (PMID 33292783, 2020). "We analyzed the expression of PD-1 on T cells and detected highly significant increased frequencies of PD-1-expressing CD8+ and CD4+ T cells in the tumor (p < 0.0001)." (PMID 32664318, 2020). "CTLA-4 blockade stimulates anti-tumor immunity by increasing the expansion of CD45RO+ICOS+PD-1lowTBET+ Th1-like CD4+ effector and also exhausted-like CD8+ T cells." (PMID 33519807, 2020). "Despite significance being reached only on the extra-tumor immune component, a reduction of CD4 (p = 0.0066), CD8 (p = 0.0061), and PD-1 (p = 0.0196) signals on stromal cells of patients with high inflammatory profile was also observed." (PMID 32646072, 2020). "Within recent years, growing interest have been on MHC class II neoantigens and the important role of CD4+ T cells in tumor recognition and in generating a strong anti-tumor response." (PMID 32226429, 2020).
tumor (continued). "The greater capability of long peptides to induce anti-tumor immunity was related but not limited to CD4+ T cell responses." (PMID 32483434, 2020). "Staining with Mitospy Orange clearly indicated a significantly increased mitochondrial membrane potential in tumor-infiltrating CD4+ and CD8+ T cells from treated compared with control mice; this was observed in non-regressor as well as regressor mice." (PMID 33093155, 2020). "Along the perimeter of the RFA-treated tumour tissue they found intense infiltrations of CD4+ and CD8+ lymphocytes following resection." (PMID 32748119, 2020). "It has been demonstrated that 5–30% of CD4+Foxp3+Tregs expressed a high level of granzyme B in tumor environments." (PMID 33519807, 2020). "It remained to be established the mechanism through which MHC class II-restricted CD4+ T cells would act in vivo to protect the animals from tumor growth." (PMID 33138029, 2020). "The primary rationale of checkpoint blockade therapy was to inhibit the immunosuppressive PD-L1/PD1 interaction between tumor cells and T cells that hampers the activity of CD4+ and CD8+ T cells." (PMID 33066260, 2020). "It is well‐established that CD4+ T cells and especially Th1 cells play a key role in promoting anti‐tumor cellular immunity, mediated via their “helper” function." (PMID 32594569, 2020). "This activity attracts more specific T cells infiltrating into the tumor microenvironment (TME) to comprise the T cell receptor/MHC/TSA complex, eventually activating the immune response and tumor killing effects of CD4+ T cells and CD8+ T cells." (PMID 32158356, 2020). "CD4+ memory T cells are an important component of the tumor microenvironment (TME) and affect tumor occurrence and progression." (PMID 33816214, 2020). "These CD4+ T cells are shown to suppress the anti-tumor cytotoxic T-cell activity, by counteracting IFN-γ mediated immune response." (PMID 33256089, 2020). "Blimp-1 was critical not only to the expression of GzmB by CD4+ T cells but also to αCTLA-4-driven anti-tumor immunity, as Blimp-1-deficient T cells were unable to control MCA205 tumor growth when mice were treated with αCTLA-4." (PMID 31924474, 2020). "Because the cells that promote antitumour immunity are CD8+ T cells, CD4+ Th1 cells, NK cells, and mature DCs, tumours that have this predominant infiltration pattern respond better to antitumour immunotherapy." (PMID 32610601, 2020). "Tumour microenvironment components, especially tumour infiltrating immune cells, such as B cells, CD+8 T cells, CD4+ T cells, macrophages, neutrophil and dendritic cells, playing a pivotal role in cancer occurrence and progression." (PMID 32757436, 2020). "Immune cells like non-tumor reactive CD4 and CD8 T cells, B cells, eosinophils, macrophages, follicular dendritic cells (FDCs) invade the malignant tissue." (PMID 32796826, 2020). "In PDAC, M2-polarized macrophages have tumor-promoting effects by releasing immunosuppressive cytokines and inducing Th2 and regulatory T-cell differentiation of CD4+ T cells." (PMID 32865617, 2020). "The immune cell depletion model showed that the anti-tumor effects of liothyronine depends on CD4+ T cells, CD8+ T cells and NK cells." (PMID 32894141, 2020). "CD4+ memory T cells inhibit the growth of tumor cells by promoting the proliferation of CD8+ memory T cells." (PMID 33043974, 2020). "The most studied predictive biomarkers for response to checkpoint inhibitors include tumor mutational load, PD-1 expression, CD4/CD8 lymphocyte ratio, the percentage of tumor-infiltrating lymphocytes, and several methods of establishing immune scores." (PMID 33327392, 2020). "As the activation and memory status of CD8+ and CD4+ Eff T cells is closely related to tumor control, next we determined the effect of AZD6738 on tumor recurrence." (PMID 32461345, 2020).
tumor (continued). "Analysis of tumor‐infiltrating lymphocytes (TILs) by IHC staining showed that Y‐27632‐treated or anti‐PD‐1 antibody‐treated tumor had significantly increased CD4+ and CD8+ T‐cell infiltration." (PMID 32941674, 2020). "Pre-clinical studies revealed that CD4 CAR-NK cells reduced tumor burden and prolonged overall survival, thus demonstrating therapeutic effects in vivo." (PMID 32707982, 2020). "Compared to the single treatment and the complementary supplement of TNuF, the preventive TNuF supplement with RT (PTRN group) provided the greatest restoration of the CD4+/CD8+ ratio in tumor tissues." (PMID 32872195, 2020). "The anti-tumor immune response was attributed to the higher concentration of CD4+ and CD8+ lymphocytes and NK cells infiltration at the tumor site." (PMID 33066447, 2020). "Paradoxically, higher numbers of CD4+ cells have been correlated with disease progression in 4T1 tumor-bearing mice." (PMID 32542046, 2020). "Antitumor immunity is initiated by APCs, such as DCs, which capture tumor antigens from tumor cells and induce the DCs and CD4/CD8 response in spleen." (PMID 32595493, 2020). "CD4+CD25+ regulatory T cells (Tregs) play an important role in anti-tumor immune responses, and a poor prognosis and declining survival rates are closely related with high Treg expression in cancer patients." (PMID 32968155, 2020). "This means that with the high expression of 11 genes, CD4 + level in patients decreases gradually, greatly reducing the patients anti-tumor ability." (PMID 33101383, 2020). "The results showed that PLXND1 had the most significant correlation with tumor-infiltrating lymphocytes including Tfh cells, macrophages, Tcm_CD4 cells, and mast cells." (PMID 33489909, 2020). "JNJ77 treatment non-significantly reduced tumour weight and spleen weight, while it significantly decreased the percentage of tumour-infiltrating CD4+ T lymphocytes and further reduced the percentage of Tregs in TDLN." (PMID 31748740, 2020). "This suggests that PD-1/combination treatment promotes CD4+ TH1 cells, a functional subset associated with increased tumor immunity." (PMID 33193386, 2020). "Treatment with sunitinib decreased the number of suppressive cells, enhanced CD8 and CD4 cell tumor infiltration and improved survival in tumor-bearing mice." (PMID 32983165, 2020). "Although their approach differed from ours (general immune status versus microenvironment of tumor), there are several features common to both approaches, such as increasing CD4+FOXP3+ and increased TGFβ-Treg cells with ROS competition." (PMID 32977478, 2020). "On the other hand, the percentage of Foxp3 + Treg in CD4 + T cells within the tumour was significantly decreased with the administration of anti-PD-1 antibody (Control; 39.5 ± 6.7%, 4H2; 21.2 ± 3.2%." (PMID 31914969, 2020). "On the other hand, the percentage of T-cells (CD4 or CD8) or macrophages in the tumor microenvironment was similar between PMBCL and DLBCL–NOS." (PMID 32366834, 2020). "IDO+ DCs converted CD4+ T cells to regulatory T cells, which suppressed the anti-tumour functions of CD8+ T cells." (PMID 33143170, 2020). "The higher positive correlation with macrophage M0 were T cells gamma delta, T cells CD4 memory activated and NK cells activated, while the higher negative correlation were plasma cells, neutrophils and mast cells resting in non-tumor tissues." (PMID 32850758, 2020). "Further, the MDSC percentage in PBMC from CRC patients was significantly greater than from healthy donors and both MDSC and Treg (CD4+CD25highFOXP3+) populations in PBMCs significantly decreased following tumor resection." (PMID 32575843, 2020). "Here, definitely the presence and availability in the tumor microenvironment of sufficient amounts of key cytokines, such as IL-2 and IFNɣ produced by anti-tumor primed CD4+ T cells, facilitated the activation and function of CD8+ CTL effectors." (PMID 33138029, 2020).